NPTN (neuroplastin)
Diseases named in the same sentence as NPTN in open-access papers:
NPTN is named in the same sentence as 45 diseases in open-access papers, as found by Europe PMC text mining. Sharing a sentence is not in itself a finding about the gene and the disease. The quoted sentences say what the papers report.
schizophrenia (5 papers, 2020 to 2021). A major psychotic disorder characterized by abnormalities in the perception or expression of reality. "Neuroplastin loss or disruption of molecular pathways related to neuronal processes has been linked to various neurological diseases, including dementia, schizophrenia, and Alzheimer’s disease." (PMID 34680901, 2021). "Subsequent genetic studies of patients with schizophrenia identified three single-nucleotide polymorphisms (SNPs) in the 5′-upstream region of NPTN that were strongly correlated to schizophrenia." (PMID 34680901, 2021). "Our recent review summarizes the role of neuroplastin and its binding partners in molecular pathways underlying neuropsychiatric and neurodegenerative diseases such as schizophrenia, depression, or Alzheimer’s disease." (PMID 34975406, 2021). "In a study that included 200 patients with schizophrenia and 278 healthy volunteers, variations in SNPs in the 5′-upstream regions of NPTN were found, which may confer to genetic susceptibility to schizophrenia." (PMID 34282131, 2021). "In addition, a haplotype that was more frequently found in controls than patients with schizophrenia could be associated with mitigating the onset risk of schizophrenia, as its reduced transcriptional activity may interfere with excessive homophilic NPTN–NPTN interaction." (PMID 34282131, 2021). "In rat models displaying schizophrenia-like symptoms after injection of the two different psychostimulants methamphetamine (MAP) or phencyclidine (PCP), neuroplastin was significantly up-regulated." (PMID 34680901, 2021).
deafness (4 papers, 2018 to 2022). An inherited or acquired condition characterized by the complete loss of the ability to hear from one or both ears. "The recent finding that particular mutations in the neuroplastin gene (Nptn) can lead to deafness attracted interest in the functions of neuroplastin in the hearing system." (PMID 33844052, 2021). "Our combined data show, that the complete loss of neuroplastin results in deafness already in the auditory periphery that explains the inability of adult Nptn−/− mice to behaviorally respond to auditory stimuli simply due to peripheral hearing loss." (PMID 33844052, 2021). "Mutations in Neuroplastin have already been implicated in deafness in mice." (PMID 35100259, 2022). "Interestingly, PMCA2 loss of function mutations result in deafness in mice and human, verifying that the interaction of neuroplastin with PMCA is decisive for Ca2+ extrusion." (PMID 34680901, 2021). "Recent studies have reported that mutation of the NPTN gene results in deafness in mice." (PMID 29974341, 2018). "The hearing threshold of 4-month-old adult Nptn−/− mice (n = 3, 90 dB) was significantly higher than in wild-type littermate controls (n = 3, 30–40 dB; p < 0.0001) and revealed deafness in Nptn−/− mice similar as reported for the previously characterized neuroplastin mutants." (PMID 33844052, 2021). "Recently, the neuroplastin gene was identified as a deafness gene." (PMID 33844052, 2021). "Together, these recent findings clearly confirm NPTN as a novel deafness gene." (PMID 29974341, 2018). "Importantly, while to date there are no reports of NEUROPLASTIN mutations directly causing hearing loss in patients, variants in this gene may be involved in human deafness in combination with other genetic lesions." (PMID 35100259, 2022). "In this study, we investigate with targeted mutants that cannot express altered or truncated neuroplastin isoforms whether the complete absence of neuroplastin or its loss in adulthood result in deafness and interfere with the central auditory perception and processing." (PMID 33844052, 2021). "In conclusion, our data show that in the complete absence of neuroplastin during development the peripheral hair cells fail resulting in deafness and prevention of auditory signal transmission to the AC." (PMID 33844052, 2021). "The residual cortical activities detectable in some young Nptn−/− mice might indicate initial development to a residual activity which is then lost with age leading to deafness in the absence of neuroplastin." (PMID 33844052, 2021). "The complete lack of neuroplastin during development leads to deafness." (PMID 33844052, 2021).
Alzheimer disease (3 papers, 2019 to 2021). A progressive, neurodegenerative disease characterized by loss of function and death of nerve cells in several areas of the brain leading to loss of cognitive function such as memory and language. "In conclusion, our preliminary results strongly indicate that altered hippocampal expression of cell‐adhesion glycoprotein neuroplastin in Alzheimer's disease is most probably related to a tissue plasticity response in neurodegeneration." (PMID 30488668, 2019). "Here, we investigated the hippocampal expression of brain‐specific neuroplastin isoform (Np65), its relationship with amyloid and tau pathology in Alzheimer's disease (AD), and potential involvement of neuroplastin in tissue response during the disease progression." (PMID 30488668, 2019). "Therefore, in this study we analysed the expression and distribution of neuroplastin immunoreactivity in human hippocampal sections derived from brains of individuals with Alzheimer's disease (AD) and control sections obtained from cognitively normal subjects." (PMID 30488668, 2019). "Using immunohistochemical techniques, this study showed that the expression of neuroplastin, CAM known to be involved in processes of learning, memory and cognition, is consistently and significantly changed in the major hippocampal areas in Alzheimer's disease." (PMID 30488668, 2019).
autism (3 papers, 2017 to 2021). Persistent deficits in social interaction and communication and interaction as well as a markedly restricted repertoire of activity and interest as well as repetitive patterns of behavior. "The genes involved in both neural development and cell–cell adhesion are 6 protocadherins (part of the cadherin family), the autism susceptibility gene NRXN1 (neurexin), and NPTN (neuroplastin), which has been associated with cortical thickness and intellectual ability in humans." (PMID 31628250, 2019).
breast carcinoma (3 papers, 2004 to 2021). "In our study, the NPTN expression was persistently down-regulated in MDA-MB-231 breast cancer cells upon ITGB3 knockdown." (PMID 33083904, 2021). "In a study screening for potential tumor antigens from breast cancer patients, neuroplastin was identified and showed strongly increased immunoreactivity in invasive carcinoma tissues." (PMID 34680901, 2021). "It is known that the high expression of neuroplastin (NPTN) in breast carcinomas with distant metastasis is related to a significant increase in tumor growth and angiogenesis." (PMID 33083904, 2021). "Moreover, over-expression of neuroplastin in a breast-cancer-derived cell line strongly increased tumor growth and angiogenesis, as well as the production of vascular endothelia growth factor (VEGF), suggesting an angiogenic mechanism regulated by VEGF in the aberrant neuroplastin-expressing tumors." (PMID 34680901, 2021).
cognitive deficits (3 papers, 2021 to 2025). "Furthermore, the potential cleavage of neuroplastin by BACE1 or other proteases, and its successive cognitive impairment and neurodegeneration, should be addressed." (PMID 34680901, 2021). "Although further studies on the cleavage of Np by BACE1 were not conducted, an attractive hypothesis is that increased neuroplastin cleavage by BACE1 could result in the cognitive deficits observed in AD." (PMID 34680901, 2021).
dementia (3 papers, 2015 to 2023). Loss of intellectual abilities interfering with an individual's social and occupational functions. "Furthermore, additional proteins which were consistently altered in both the FLNC-, GRN- and VCP-unique datasets, e.g. GFAP, NPTN, DBI, PRDX6, MARCKS and BSN, are closely associated with cognitive function, dementia and pathological aging." (PMID 26555887, 2015).
lung carcinoma (3 papers, 2020 to 2025). "Neuroplastin (NPTN), which encodes a type I transmembrane protein belonging to the Ig superfamily, can promote lung cancer progression through epithelial-mesenchyme transition (EMT)." (PMID 37700319, 2023). "Our recent study revealed an important role of the neuroplastin (NPTN)β downstream signal in lung cancer dissemination in the lung." (PMID 32490214, 2020). "Five of the eight NSCLC/lung cancers harboring a RASGRF fusion were adenocarcinomas (corresponding to the NSCLCs containing PACSIN2-RASGRF1, DLG1-RASGRF1, RP2-RASGRF1, NPTN-RASGRF1, and OCLN–RASGRF2)." (PMID 40615519, 2025).
amnesia (2 papers, 2021). Pathologic partial or complete loss of the ability to recall past experiences ( AMNESIA, RETROGRADE) or to form new memories ( AMNESIA, ANTEROGRADE). "Recently, intellectual abilities, creativity, and amnesia have been associated with neuroplastin, a cell recognition glycoprotein of the immunoglobulin superfamily that participates in synapse formation and function and calcium signaling." (PMID 34680901, 2021).
diabetes (2 papers, 2020 to 2024). "Thus, inhibiting NPTN function or expression could be a good strategy to prevent or reverse β cell failure or loss in diabetes." (PMID 39666939, 2024).
Hearing impairment (2 papers, 2021 to 2022). A decreased magnitude of the sensory perception of sound. "Moreover, while to date no NPTN mutations have been reported in patients with hearing loss, this has focused on searching for homozygous or compound heterozygous NPTN lesions." (PMID 35100259, 2022). "This study investigates whether the complete absence of neuroplastin or the loss of neuroplastin in the adult after normal development lead to hearing impairment in mice analyzed by behavioral, electrophysiological, and in vivo imaging measurements." (PMID 33844052, 2021).
autism spectrum disorder (1 paper, 2021). A spectrum of developmental disorders that includes autism, and Asperger syndrome. "In conclusion, genetic association studies suggest a link of neuroplastin to autism spectrum disorder, but the role of NPTN in ASD still needs to be specifically addressed." (PMID 34680901, 2021).
bipolar depression (1 paper, 2025). "Many shared upregulated glycopeptides in unipolar and bipolar depression were derived from multiple glycosylation sites of NPTN, THY1, CA2D1, and SHPS1 proteins." (PMID 40671800, 2025). "Another noteworthy finding was the dysregulated glycosylation of neuroplastin, which was significantly increased on multiple sites in both unipolar and bipolar depression." (PMID 40671800, 2025).
cardiac hypertrophy (1 paper, 2025). "Neuroplastin is upregulated under ER stress and can induce inflammation via NF-kB activation, while trans-acting transcription factor 1 (also known as Sp1) is associated with MI and cardiac hypertrophy." (PMID 40332511, 2025).
fragile X syndrome (1 paper, 2014). A genetic syndrome caused by mutations in the FMR1 gene which is responsible for the expression of the fragile X mental retardation 1 protein.
insulinoma (1 paper, 2024). "Here, we generate pancreatic β cell–specific Nptn KO mice and Nptn KO Rat insulinoma cell line INS-1 832/13 to investigate the roles of NPTN in pancreatic β cells." (PMID 39666939, 2024).
male infertility (1 paper, 2021). The inability of the male to effect fertilization of an ovum after a specified period of unprotected intercourse. "The loss of neuroplastin affects cellular functions as Ca2+ homeostasis, long-term-potentiation, synapse formation, and more resulting ultimately in pronounced deficits including male infertility, depression-like behavior, and learning and memory deficits in Nptn mutants." (PMID 34975406, 2021).
type 1 diabetes (1 paper, 2020). "Our data demonstrate that MANF mitigates inflammation and cell death by suppressing the NPTN-mediated inflammatory signal in a cell model of type 1 diabetes." (PMID 33299977, 2020).
cancer (10 papers, 2009 to 2024). A tumor composed of atypical neoplastic, often pleomorphic cells that invade other tissues. "Receptors of S100A9, including TLR4, RAGE, CD147, MCAM and NPTN are expressed in multiple cell types, such as cancer cells, MDSCs, macrophages and NK cells." (PMID 38713229, 2024). "Compared with that of other receptors, the functions and related mechanisms of NPTN in tumor cells are relatively less known, and further studies should aim to clarify the involvement of NPTN in the growth, migration, and angiogenesis of different cancers." (PMID 37701037, 2023). "The first evidence linking NPTN to cancer came from a bioinformatic analysis showing that NPTN was one of 166 genes with an altered expression in colorectal adenomatous polyps." (PMID 34680901, 2021). "The receptor for SDF-1 (SDFR-1, or neuroplastin) is expressed by prostate stem cells 48, indicating that in cancer SDF-1 signalling pathways are likely to be important." (PMID 19040209, 2009). "There were few studies investigating the function of NPTN in cancer." (PMID 37587479, 2023). "It has been reported that various cancer-related genes (EpCAM, VIM, and NPTN, among others) increase in these immune cells." (PMID 36012405, 2022).
tumor (9 papers, 2012 to 2023). "An in vivo experimental study substantiated over-expression of NPTN can cause significant increase in tumor growth and angiogenesis." (PMID 37587479, 2023). "Moreover, in breast cancer cells, overexpressed-NPTN contributes to tumor growth and angiogenesis in vivo, which is related to the increased VEGF production in microenvironmental hypoxia." (PMID 37701037, 2023). "Moreover, NPTN was highly expressed in circulating tumor cells (CTCs)." (PMID 33083904, 2021). "Phenotypes underlying such clustering patterns showed that CTCs maintained higher expression than all tumor cell lines for FOXC1, KRT18, PTEN, NPTN, TGFß1, KRT8, ZEB2, and CXCR4." (PMID 22586443, 2012).
neurodegenerative disease (2 papers, 2019 to 2021). A disorder of the central nervous system characterized by gradual and progressive loss of neural tissue and neurologic function. "Data from animal models suggest a role for neuroplastin in pathways affected in neuropsychiatric and neurodegenerative diseases." (PMID 34680901, 2021). "Neuroplastin's role in the molecular mechanisms entailing neurodegenerative diseases is yet to be elucidated and requires further studies." (PMID 30488668, 2019). "While developmental dysfunctions of neuroplastin-mediated synaptic processes may be more related to neuropsychiatric diseases, neurodegenerative diseases may instead involve neuroplastin-related alterations in synaptic calcium extrusion." (PMID 34680901, 2021). "In this review, we will focus on recent studies of the cell recognition molecule neuroplastin (Np) and its gene (Nptn/NPTN) in relation to psychiatric and neurodegenerative diseases." (PMID 34680901, 2021). "The function of the pairing of neuroplastin–PMCA must be regarded with respect to regulation of Ca2+ homeostasis, Ca2+ signal transduction, and synaptic activity, which are dysfunctional in neuropsychiatric diseases like ASD and SZ and neurodegenerative diseases such as AD." (PMID 34680901, 2021).
colorectal (1 paper, 2025). "Consequently, we selected eight statistically significant TACTs—EPCAM, KRT19, ERBB2, MKI67, MCAM, FOXA2, SNAI2, and NPTN—which we designated as colorectal TACTs (C-TACTs)." (PMID 40003943, 2025).
heart disease (1 paper, 2021). "Not surprisingly, the widespread expression of neuroplastin in nearly all organs may result in the discovery of further pathological conditions influenced by neuroplastin, e.g., within the immune system or in heart disease." (PMID 34680901, 2021).
immune diseases (1 paper, 2017). "In summary, our results define Neuroplastin as an essential partner for PMCAs and thus as a potential target for drug therapies on immune diseases related to impaired Ca2+ homeostasis in T cells." (PMID 28827723, 2017).
neurodevelopmental disorder (1 paper, 2019). A behavioral and cognitive disorder with onset during the developmental period that involves impaired or aberrant development of intellectual, motor, or social functions. "A number of genes differentially expressed in THRA mutation-containing cells, including the cell surface dystroglycan receptor NRXN1 (neurexin) and the transmembrane protein NPTN (neuroplastin), have also been implicated in other neurodevelopmental disorders." (PMID 31628250, 2019).
NPTN also shares sentences with these, for which no sentence is quoted: infection (5 papers); Anxiety (3); cognitive disease (2); erythroleukemia (2); neurological diseases (2); Splenomegaly (2); Stroke (2); adenocarcinoma (1); bacterial infection (1); cognitive (1); depression (1); epilepsy (1); ischemia (1); ischemic stroke (1); mastitis (1); Parkinson disease (1); polycythemia (1); retinal degeneration (1); Rett syndrome (1); Wolfram syndrome (1).